MAP2K1 (mitogen-activated protein kinase kinase 1)
Diseases named in the same sentence as MAP2K1 in open-access papers (continued):
Sharing a sentence is not in itself a finding about the gene and the disease.
lung adenocarcinoma (31 papers, 2012 to 2025). A carcinoma that arises from the lung and is characterized by the presence of malignant glandular epithelial cells. "In lung adenocarcinoma, mutations in amino acid residues 53–67 in exon 2 account for about 86% of all MAP2K1 mutations." (PMID 31827134, 2019). "MAP3K14 and MAP2K1 may serve as potential therapeutic targets in the treatment of lung adenocarcinoma in the future." (PMID 33442956, 2021). "Besides, MAP2K1 and MAP2K4 mutations can be related with MAPK pathway activity as identified in the TCGA lung adenocarcinoma original article." (PMID 32998690, 2020).
metastatic melanoma (31 papers, 2009 to 2025). A melanoma that has spread from its primary site to another anatomic site. "In this study, through analysis of the sequencing and survival data for several public cohorts with metastatic melanoma, we investigated the association between MAP2K1/2 mutations and the response to anti-CLTA-4 and anti-PD-1 immunotherapies." (PMID 35069558, 2021). "In one report, a patient with triple wild-type (BRAF/NRAS/NF1 WT) metastatic melanoma with two missense mutations in MAP2K1 showed a partial response to MEK inhibitor trametinib, followed by progression of disease after two months." (PMID 32483240, 2020). "The protein product of Map2k1 is inhibited by cobimetinib, approved to treat unresectable or metastatic melanoma." (PMID 35454087, 2022). "Trametinib is a pyridopyrimidine that is currently employed as treatment for metastatic melanoma through direct inhibition of mitogen-activated protein kinase kinase 1 and 2 (MEK1/2), an upstream signaling protein of ERK activation." (PMID 35755835, 2022). "To investigate whether MAP2K1/2 mutations are also associated with a favourable clinical response to anti-PD-1/L1 therapy, we performed data analysis using a pooled cohort consisting of three public cohorts of 253 metastatic melanoma patients treated with anti-PD-1 agents." (PMID 35069558, 2021). "Trametinib, a selective inhibitor of mitogen‐activated protein kinase kinase 1 (MEK1) and MEK2, significantly improves progression‐free survival compared with chemotherapy in patients with BRAF V600E/K mutation–positive advanced or metastatic melanoma (MM)." (PMID 27172483, 2016). "Therefore, the predictive value of MAP2K1/2 mutation in metastatic melanoma might be specific to anti-CTLA-4 therapy, rather than anti-PD-1/L1 therapy." (PMID 35069558, 2021).
ovarian carcinoma (29 papers, 2003 to 2025). A malignant neoplasm originating from the surface ovarian epithelium. "High expression of MAP2K1 is significantly associated with the development of ovarian cancer and platinum resistance." (PMID 36110943, 2022). "Pimasertib, an inhibitor of MAP2K1, has been developed for the treatment of ovarian cancer." (PMID 36110943, 2022). "We further performed correlation analysis of GPR12 mRNA level with ERK1/2 cascade expression including MAP3K1, MAP2K1, MAP2K2, and MAPK1 by using ovarian cancer data from TCGA database." (PMID 35903681, 2022).
RASopathies (29 papers, 2014 to 2025). "In this study, a somatic in-frame deletion, p.(Gln58_Glu62del), in MAP2K1 was identified in FCD type I. Germline variants of MAP2K1 have been reported in patients with RASopathy, such as cardio-facio-cutaneous syndrome." (PMID 36864519, 2023). "Many of the RASopathy-associated genes are in gene families: RAF (BRAF and RAF1), RAS (HRAS, KRAS, MRAS, NRAS, RIT1, and RRAS2), MAP2K (MAP2K1 and MAP2K2), and SOS (SOS1 and SOS2)." (PMID 40496714, 2025). "CFC syndrome is a RASopathy associated with germline mutations in KRAS, BRAF (non-V600E) and MAP2K1 (MEK1)/MAP2K2 (MEK2)." (PMID 33800195, 2021). "Individuals with Noonan Syndrome (MIM: 163950) comprise ~50% of all RASopathy cases and mutations have been observed in multiple genes, including PTPN11/SHP2, SOS1, SHOC2, KRAS, NRAS, LZTR1 (MIM: 600574), RAF1/CRAF, and MAP2K1/MEK1." (PMID 31017896, 2019). "Cardio-facio-cutaneous syndrome (CFC) is a rare RASopathy associated with mutations in BRAF, KRAS, MEK1 (MAP2K1) and MEK2 (MAP2K2)." (PMID 29590634, 2018). "The RASopathies, collectively, are a spectrum of genetic syndromes caused by mutations in genes involved in the RAS/ mitogen-activated protein kinase (MAPK) pathway, including but not limited to PTPN11, NRAS, KRAS, HRAS, BRAF, and MAP2K1." (PMID 39385823, 2024). "In addition, we verified by exomeanalysis that the patient did not have any pathogenic variants in the genes associatedwith Noonan Syndrome and other rasopathies (PTPN11,SHOC2, KRAS, CBL,SOS1, RAF1, HRAS,NRAS, RASA1, SPRED1,BRAF, MAP2K1, MAP2K2, RIT1 andRRAS)." (PMID 27561113, 2016). "A KRAS p.Q61R mutation was found in both the affected and unaffected bone of one MAP2K1 mutation-negative patient with skin lesions consistent with RASopathy, who likely has melorheostosis as part of a more complex early embryonic mosaic RASopathy, which will be reported separately." (PMID 29643386, 2018). "Multigene panel for common RASopathy genes that includes BRAF, MAP2K1, MAP2K2, KRAS and YWHAZ usually detects up to 90% of individuals with CFC and it is the preferred initial test." (PMID 38136934, 2023). "Germline mutations in MAP2K1 (which encodes MEK1) and MAP2K2 (MEK2) can cause cardio-facio-cutaneous (CFC) syndrome, a known RASopathy, although there are no reports of bAVMs in these patients." (PMID 39899215, 2025).
cardiac hypertrophy (25 papers, 2009 to 2025). "Meanwhile, MAP2K1 inhibitors could rescue myocardial hypertrophy and fibrosis and improve cardiac function." (PMID 38085668, 2023). "For cardiac hypertrophy, the highest MGDT score was obtained for miR-449a/MAP2K1/arsenic trioxide." (PMID 30514363, 2018).
non-small cell lung carcinoma (25 papers, 2013 to 2026). A group of at least three distinct histological types of lung cancer, including non-small cell squamous cell carcinoma, adenocarcinoma, and large cell carcinoma. "Furthermore, a phase I study of binimetinib in patients with non-small cell lung cancer, among whom 8 harbored MAP2K1 mutations, reported an overall response rate of 42.8%." (PMID 36013219, 2022).
thyroid cancer (25 papers, 2010 to 2025). "Protein targets, ESR1 and MAP2K1, act through prolactin, thyroid cancer, endocrine resistance, GnRH secretion, and estrogen signaling pathways." (PMID 38338298, 2024). "Among these proteins, BRAF and MAP2K1 were affected by phosphorylation in early-stage thyroid cancer cells." (PMID 31126066, 2019). "The increased expression of MAP2K1 is due to the positive regulation of NFE2L1 with phosphorylation, which could promote the progression of the tumor cell cycle and increase the growth and proliferation of thyroid cancer cells." (PMID 31126066, 2019). "Hence, inhibition of the mitogen-activated protein kinase kinase-1 and -2 (MEK-1 and -2) downstream of RAF (rapidly accelerated fibrosarcoma) could sensitize RAI refractivity in thyroid cancer." (PMID 31533238, 2019).
glioblastoma (23 papers, 2015 to 2025). The most malignant astrocytic tumor (WHO grade IV). "Circ_ASAP1 promotes tumorigenesis and the temozolomide (TMZ) resistance of glioblastoma via the NRAS proto-oncogene, GTPase (NRAS)/mitogen-activated protein kinase kinase 1 (MEK1)/extracellular signal-regulated kinase 1 and 2 (ERK1-2) signaling pathway." (PMID 34829818, 2021). "On the other hand, a recent study showed that overexpression of miR-424 strongly suppressed cell proliferation and migration rate in glioblastoma cells, by targeting genes such as KRAS, RAF1, and MAP2K1, from the epidermal growth factor receptor (ERBB) signaling pathway." (PMID 37047673, 2023).
hepatocellular carcinoma (22 papers, 2012 to 2025). A malignant tumor that arises from hepatocytes. "Five genes with de novo damaging alleles PIK3CA, TLN1 CYLD, and MAP2K1, are linked with cholangio- and hepatocellular carcinomas in addition to congenital syndromes and conditions related to tissue overgrowth." (PMID 27955658, 2016). "Six genes carrying DNVs were associated with human developmental disorders involving epithelial, connective or bone morphologies (PXDN, RTEL1, ANKRD11, MAP2K1, CYLD, ACAN) and four linked with cholangio- and hepatocellular carcinomas (PIK3CA, TLN1 CYLD, MAP2K1)." (PMID 27955658, 2016).
prostate carcinoma (22 papers, 2011 to 2025). A carcinoma that arises from epithelial cells of the prostate gland. "that MAP2K1 phosphorylates FADD in prostate cancer—was also reported in an independent study." (PMID 27078000, 2016). "MED28 is highly expressed in breast, colon, and prostate cancers, and MED28 induces cancer cell proliferation via the mitogen-activated protein kinase kinase-1 (MAP2K1) signaling pathway." (PMID 30970566, 2019). "Genes involved in steroid synthesis included CYP21A2, HSD17B2, ITGA6, IDI2, MAP2K1, PMVK, TSPO, and may correspond to androgen dependent growth of prostate cancer." (PMID 32226005, 2020). "Meanwhile, there are several genes which mediate the miR-34a induced tumor growth inhibition, such as BCL2, E2F3 and MYCN in neuroblastoma, mitogen-activated protein kinase kinase 1 (MEK1) in human chronic myelocytic leukemia cell line K562 and SIRT1 in prostate cancer PC3 cells." (PMID 22457788, 2012). "In prostate cancer, a serum protein complex composed of native α2-M and prostate-specific antigen was shown to bind GRP78, resulting in the activation of mitogen-activated protein kinase kinase 1/2 (MEK1/2), ERK1/2, S6K, and Akt pro-survival pathways and the increase of DNA and protein synthesis." (PMID 33299639, 2020).
Noonan syndrome (21 papers, 2013 to 2025). "Importantly, the finding of a MAP2K1 (Noonan's syndrome) damaging variant (c." (PMID 27955658, 2016). "Somatic pathogenic variants in genes of the RAS/MAPK signaling pathway, in turn, are causative for RASopathies such as Noonan syndrome (BRAF, MAP2K1, PTPN11, or RAF1 variants), Costello syndrome (HRAS variants) as well as other Noonan-like syndromes." (PMID 38835734, 2023). "Mutations associated with Noonan syndrome alone include CBL, BRAF, KRAS, LZTR1, MAP2K1 (MEK1), NRAS, PTPN11, RAF1, RIT1, SOS1 and SOS2." (PMID 38550930, 2023). "Four of the proteins are linked to various forms of the Noonan syndrome (CBL, MAP2K1, RAF1 and SOS), 5 to various types of tumors (MAPK1, PRKCQ, ABL1, GRAP2 and RAS) and one to an autoimmune disorder (RASGRP1)." (PMID 28448599, 2017). "Noonan syndrome is a cluster of monogenic conditions involving several genes in the RAS-MAPK pathway (PTPN11, SOS1, SHOC2, MAP2K1/2 and KRAS in the included paper)." (PMID 36729042, 2023). "Over the years, several other genes involved in Noonan syndrome (KRAS, SOS1, RAF1, MAP2K1, BRAF, NRAS, RIT1, and LZTR1) have been identified, acting at different levels of the RAS-mitogen-activated protein kinase pathway." (PMID 38254922, 2023).
liver cancer (20 papers, 2014 to 2025). An epithelial or non-epithelial malignant neoplasm that arises from the liver. "Our study shows that the abnormal expression of MAP2K1 may predict the occurrence of liver cancer, especially in male patients." (PMID 40587753, 2025). "At time of writing, MAP2K1 has not been directly implicated in liver cancer; however the MAPK signaling pathway has been identified as important for PLC." (PMID 28333948, 2017). "The interaction between MAP2K1 (MEK1) and YAP is required for the proliferation of liver cancer cells." (PMID 38622197, 2024).
cardio-facio-cutaneous syndrome (18 papers, 2010 to 2024). "Interestingly, we identified a pathogenic variant (MAP2K1 c.389A>G; p.Tyr130Cys) known to be frequently associated with Cardiofaciocutaneous syndrome." (PMID 31057598, 2019). "Costello syndrome(CS) has been associated with mutations in HRAS, and cardio-facio-cutaneous syndrome(CFCS) with BRAF, MAP2K1, MAP2K2 and KRAS." (PMID 37964950, 2023). "High and narrow palate with submucous clefting is a typical craniofacial feature in cardiofaciocutaneous syndrome, which is caused by mutations in KRAS, BRAF, MAP2K1 and MAP2K2." (PMID 34897389, 2022).
leukemia (17 papers, 2014 to 2025). A malignant (clonal) hematologic disorder, involving hematopoietic stem cells and characterized by the presence of primitive or atypical myeloid or lymphoid cells in the bone marrow and the blood. "WWOX physically interacts with MEK1 (Mitogen-Activated Protein Kinase Kinase 1), and that dissociation of the protein complex results in apoptosis of leukemia cells." (PMID 25537520, 2014). "Although we could not detect clear changes in splicing in leukemias, SRPIN340 changed the splicing of MAP2K1 in HeLa cells, suggesting that different cancer lineages may respond differently to SRPK inhibition." (PMID 26244849, 2015).
neuroblastoma (15 papers, 2007 to 2025). Neuroblastoma (NB) is the most common solid, extracranial childhood tumor. "In vitro studies of MAP2K1 mutations (K57M, G128V, Y130C) in neuroblastoma cell lines have demonstrated increased cell proliferation and autophagy." (PMID 40692796, 2025). "Likewise, sgRNAs for NRAS and MAP2K1 (MEK1), a downstream kinase of mutant NRAS, were identified among the top hits in the NRAS-mutant neuroblastoma cell line CHP-212." (PMID 27613601, 2016).
viral infection (13 papers, 2014 to 2026). "Although inhibition of both MAP2K1/2 led to a reduction in SARS-CoV-2 infection that suggested their crucial role in the viral infection process, the potential kinase-substrate relationships with viral proteins are not yet established." (PMID 40703672, 2025). "Some cases have been linked to viral infections, including Epstein–Barr virus, cytomegalovirus, human herpesviruses, and human immunodeficiency virus, as well as somatic mutations in genes such as NRAS, KRAS, MAP2K1 and ARAF." (PMID 41321345, 2025). "Overexpression of JAK1, TYK2, MAP2K1, IFNG, TRPM2, and ADCY9 significantly inhibited viral infection, whereas overexpression of SNX27, GATA4, EHMT2, PCBP2, SMARCA4, and SLX4 enhanced viral infection." (PMID 40530850, 2025).
Langerhans cell histiocytosis (12 papers, 2017 to 2026). Langerhans cell histiocytosis (LCH) is a systemic disease associated with the proliferation and accumulation (usually in granulomas) of Langerhans cells in various tissues. "Out of nine patients with Langerhans cell histiocytosis, 44.4% (4/9) exhibited a MAP2K1 mutation, and 44.4% (4/9) exhibited a BRAF mutation." (PMID 37092519, 2023). "Several other cases of successful MEK-inhibitor use in MAP2K1-mutant malignancies have been documented, primarily non-Langerhans cell histiocytosis and hairy cell leukemia." (PMID 39314226, 2024). "Histiocytic neoplasms such as Langerhans cell histiocytosis (LCH) and Erdheim–Chester disease (ECD) are characterized by various mutations in the mitogen-activated protein kinase (MAPK) pathway, including BRAF V600E, MAP2K1, and others." (PMID 41562816, 2026). "MAP2K1, which encodes MEK1, was not analyzed by next-generation sequencing, and mutations in this gene were detected in Langerhans cell histiocytosis in the absence of BRAF mutations." (PMID 28658279, 2017).
fibrosarcoma (11 papers, 2018 to 2026). A malignant mesenchymal fibroblastic neoplasm affecting the soft tissue and bone. "The extracellular signal regulated kinase 1/2 (ERK1/2)/rapidly accelerated fibrosarcoma (raf)-mitogen-activated protein kinase kinase 1 (MEK1)-mitogen-activated protein kinase (MAPK) pathway is activated, leading to increased proliferation." (PMID 32070055, 2020).
melorheostosis (11 papers, 2018 to 2025). Melorheostosis is a rare connective tissue disorder characterized by a sclerosing bone dysplasia, usually limited to one side of the body (rarely bilateral), that manifests with pain, stiffness, joint contractures and deformities. "Decades later, high‐resolution sequencing of sporadic melorheostosis revealed recurrent somatic activating mutations in MAP2K1 confined to affected bone." (PMID 41214899, 2025). "Despite no pathogenic variant detected through exome sequencing, recent studies link melorheostosis to somatic mutations, particularly in the MAP2K1, which plays a crucial role in the RAS-MAPK signaling pathway, implicated in bone remodeling and sclerosis." (PMID 40198394, 2025). "Some cases of melorheostosis result from sporadic somatic mutations in MAP2K1, which encodes MEK1 protein kinase, a key component of the RAS/MAPK signaling pathway." (PMID 41216092, 2025). "ERK1/2 activation and decreased osteoblast differentiation have also been demonstrated in the classic “dripping candle wax” form of melorheostosis, although melorheostosis is caused by MAP2K1 somatic mosaicism." (PMID 39127989, 2024). "In the literature, it is reported that isolated melorheostosis is associated with random somatic mutations of the MAP2K1 gene." (PMID 37241101, 2023). "We recently identified somatic mosaicism for gain‐of‐function mutations in MAP2K1 in patients with melorheostosis." (PMID 31485554, 2019). "The MAP2K1 mutations identified in melorheostosis patients cause substitutions in two residues of the MEK1 negative regulatory domain." (PMID 29643386, 2018). "Here, the authors use whole exome sequencing to identify somatic mutations in MAP2K1 in affected bone of melorheostosis patients which is associated with increased proliferation but delayed differentiation of cultured osteoblasts." (PMID 29643386, 2018). "Development of a diagnostic test is especially valuable because identification of somatic MAP2K1 mutations in melorheostosis raises the possibility of inhibiting MEK1 to treat melorheostotic bone lesions." (PMID 29643386, 2018). "Furthermore, isolated MAP2K1 mutations can stimulate benign bone cell proliferation, causing melorheostosis." (PMID 38978887, 2024). "In addition, isolated somatic mutations of MAP2K1 can lead to the localized benign proliferation of bone cells which results in melorheostosis." (PMID 37241101, 2023). "Our finding that three of four patients demonstrated mutations in the overlying skin raises the possibility that testing of skin for MAP2K1 mutations may be a diagnostic test for melorheostosis." (PMID 29643386, 2018). "The underlying pathophysiology of MAP2K1-positive melorheostosis might be explained by a gradual deterioration of bone microarchitecture, which subsequently triggers a periosteal reaction akin to osteomyelitis or trauma, ultimately leading to overall cortical outgrowth." (PMID 38978887, 2024). "Extremely rare osteosclerotic disorders also include Caffey disease, Lenz-Majewski hyperostotic dwarfism, trichothiodystrophy-1 with axial osteosclerosis, and melorheostosis which are caused by mutations in COL1A1, PTDSS1, ERCC2, and MAP2K1, respectively." (PMID 40198394, 2025). "The MAP2K1 oncogene plays a crucial role in human bone formation and presents opportunities for future gene therapy in treating melorheostosis." (PMID 38978887, 2024). "It has been documented that melorheostosis occurring in isolation is related to random somatic mutations of the MAP2K1 gene, which encodes the MEK1 protein kinase involved in the RAS/MAPK signaling pathway." (PMID 38978887, 2024). "The MAP2K1 oncogene is significant in the bone formation of humans and opens the potential treatment of melorheostosis by gene therapy in the future." (PMID 37241101, 2023). "MAP2K1 codes for protein MEK1 protein kinase and the activating mutations we identified in melorheostosis result in increased signaling of the RAS/MAPK pathway." (PMID 31485554, 2019).